ZNF343 (zinc finger protein 343)
Description:
May be involved in transcriptional regulation.
Synonyms: MGC10715; dJ734P14.5
Tractability: PROTAC: UniProt records ubiquitination sites on it; ubiquitination databases record sites on it.
Gene: Protein-coding gene on chromosome 20 (2,481,817 to 2,525,028, reverse strand). Ensembl gene ENSG00000088876.
Subcellular location: Nucleus
Subcellular location (Human Protein Atlas): Nucleoplasm
Pathways (Reactome):
Gene expression (Transcription): Generic Transcription Pathway
Gene Ontology:
Molecular function: protein binding; sequence-specific double-stranded DNA binding; DNA-binding transcription factor activity, RNA polymerase II-specific; RNA polymerase II transcription regulatory region sequence-specific DNA binding; sequence-specific DNA binding; zinc ion binding
Biological process: regulation of transcription by RNA polymerase II; regulation of DNA-templated transcription
Cellular component: nucleus
Genetic constraint (gnomAD): Loss-of-function variants: 11 observed, 15.15 expected, observed/expected ratio (o/e) 0.73, 90% interval 0.46 to 1.2. The upper end of that interval is the gene's LOEUF score, 1.2, which puts it in group 5 of 6, group 1 being the genes least tolerant of losing a copy. Missense variants: 658 observed, 737.83 expected, observed/expected ratio (o/e) 0.89, 90% interval 0.84 to 0.95. Synonymous variants: 248 observed, 264.09 expected, observed/expected ratio (o/e) 0.94, 90% interval 0.85 to 1.04.
Homologues: Orthologues: chimpanzee ZNF343 (99% identical), macaque ZNF343 (96% identical), Drosophila melanogaster CG3281 (22% identical), Drosophila melanogaster CG2712 (21% identical), Drosophila melanogaster Phs (19% identical). Paralogues in human: ZNF133 (52% identical), ZNF875 (50% identical), PRDM9 (47% identical), ZNF337 (46% identical), ZNF169 (46% identical), ZNF614 (35% identical), ZFP90 (34% identical), ZFP37 (34% identical), ZNF674 (33% identical), ZNF805 (33% identical), ZNF25 (33% identical), ZNF264 (33% identical), and 50 more.